CCN5 (cellular communication network factor 5)
Diseases named in the same sentence as CCN5 in open-access papers (continued):
Sharing a sentence is not in itself a finding about the gene and the disease.
Obesity (10 papers, 2016 to 2025). Accumulation of substantial excess body fat. "CCN5/WISP2 is prominently manifest in adipose tissue and has been linked to the pathogenesis of obesity, diabetes, and insulin resistance." (PMID 37794318, 2023). "CCN4/WISP-1 and CCN5/WISP-2 have roles in metabolic disorders involving glucose homeostasis, such as insulin resistance, diabetes, and obesity, and have been associated with the development and regulation of different types of cancers." (PMID 34063397, 2021). "As expected from previous reports, CCN5/WISP2 gene deficiency has been associated with mild obesity, insulin resistance, hyperglycemia, and lipotoxic cardiomyopathy." (PMID 34948212, 2021). "In this study, we observed that knockout (KO) of CCN5, which encodes a matricellular protein, caused mild obesity in mice." (PMID 30485307, 2018). "Given the known relationship between CCN5 and obesity and insulin resistance, we hypothesized that CCN5 serum levels may be associated with the risk of developing GDM." (PMID 37794318, 2023). "Given the established connection of CCN5/WISP2 with obesity, diabetes, and insulin resistance, alongside the inconsistencies in earlier research, the present study aimed to explore the association of WISP2 with risk factors in GDM patients." (PMID 37794318, 2023). "TGF-β has been shown to activate the downstream gene Smad3, which inhibits the expression of PPARγ coactivator-1α (PGC-1α) gene, potentially leading to mild obesity in individuals with reduced CCN5 expression." (PMID 37794318, 2023). "Normal CCN5 expression controls adipocyte proliferation or maturation, adipogenesis, insulin responsiveness, fibrosis, obesity, and heart function." (PMID 34948212, 2021). "Perhaps due to the mild obesity, lipid accumulation, and increased lipid oxidation, CCN5-knockout mice fed an NCD also showed mild hyperinsulinemia, hyperglycemia, and insulin resistance." (PMID 34948212, 2021). "In humans, analysis of adipose protein secretome highlights CCN5 as a key regulator of obesity and ECM interactions." (PMID 34948212, 2021). "As a novel adipokine, CCN5 expression was significantly increased in human obesity and insulin resistance." (PMID 34948212, 2021). "The phenotypes of the CCN5 KO mice characterized in this study is largely consistent with the proposed anti-obesity function of CCN5." (PMID 30485307, 2018). "Taken together, these results indicate that CCN5 KO leads to lipotoxic cardiomyopathy with mild obesity and diabetes in mice." (PMID 30485307, 2018). "In this report, we provide compelling lines of evidence showing that CCN5 KO in mice results in mild obesity and diabetes, accompanied by ectopic lipid accumulation in hearts." (PMID 30485307, 2018). "Recently, we identified WNT1-inducible signaling pathway protein 2 (WISP2/CCN5) as a novel secreted adipokine which was increased in obesity and insulin resistance in the subcutaneous adipose tissue in man9." (PMID 28240264, 2017). "Moreover, CCN5 is implicated in regulating adipocyte lineage fate, as CCN5-knockout mice exhibit lipotoxic cardiomyopathy accompanied by mild obesity and diabetes, potentially linking CCN5 to lipid droplet degradation in aging LCs." (PMID 40756763, 2025). "Additionally, CCN5 gene knockout-induced mild obesity and diabetes were observed in another study, with increased FBG levels in CCN5 knockout mice." (PMID 37794318, 2023). "Moreover, excess CCN3 induces obesity, insulin resistance, and disrupt pancreatic islets; this is similar to CCN5 knockout, demonstrating the contrasting roles played by CCN3 and CCN5 again." (PMID 34948212, 2021). "Before assessing its normal physiology, it is necessary to know where (i.e., in which tissues and cells) CCN5 is normally expressed and how the expression might be regulated (e.g., by obesity and diabetes)." (PMID 34948212, 2021). "Collectively, these data showed that CCN5 KO leads to mild obesity in mice." (PMID 30485307, 2018).
Obesity (continued). "Understanding how CCN5/WISP2 is regulated and signals is important and may be useful for developing new treatment strategies in obesity and metabolic diseases and it can also be a target in regenerative medicine." (PMID 29247377, 2018). "Thus, CCN5/WISP2 is a novel regulator of mesenchymal tissue growth and development and can, thereby, also be an important target for preventing obesity- related metabolic complications." (PMID 29247377, 2018). "In our investigation, we have detected a notable association between CCN5 and FBG levels in the serum, which stands in opposition to prior scholarly findings indicating that CCN5 could impede the onset of obesity and diabetes by repressing the TGF-β signaling cascade." (PMID 37794318, 2023). "Thus, the lack of CCN5 signaling may result in mild obesity, possibly through elevated TGF-β/Smad3 signaling activities." (PMID 34948212, 2021). "Therefore, it is conceivable that CCN5 may exert its anti-obesity effects at least partially by inhibiting the TGF-β signaling pathway." (PMID 30485307, 2018). "Alongside obesity, the mass of subcutaneous and perirenal white adipose tissues (sWAT and pWAT) and of the heart was significantly increased in NCD-fed CCN5-knockout vs. wild-type mice." (PMID 34948212, 2021). "While the effects of CCNs are diverse in many tissues, this review will focus on the role of CCN5/WISP2 and its effects in metabolic diseases, in particular obesity and diabetes." (PMID 29247377, 2018). "First, CCN5-knockout mice fed the normal chow diet (NCD) have been shown to exhibit mild obesity in comparison to wild-type littermates, despite no significant change in food intake." (PMID 34948212, 2021). "Together, CCN5 knockout would result in increased adipocyte differentiation, activated TGF-β/Smad3 pathway, and the expression of adipogenic genes, which all contribute to mild obesity." (PMID 34948212, 2021).
Insulin resistance (9 papers, 2017 to 2025). Increased resistance towards insulin, that is, diminished effectiveness of insulin in reducing blood glucose levels. "In summary, a systemic deficiency of CCN5 gene expression caused adipocyte hypertrophy, increased adipogenesis, and lipid accumulation, resulted in insulin resistance and glucose intolerance, which are further exacerbated upon HFD feeding." (PMID 34948212, 2021). "Prominent among the discoveries was that a systemic deficiency of CCN5 gene expression caused adipocyte hypertrophy, increased adipogenesis, and lipid accumulation, resulting in insulin resistance and glucose intolerance, which were further exacerbated upon high-fat diet feeding." (PMID 34948212, 2021). "Although various studies have delved into the link between CCN5 and metabolic disorders, insulin resistance, and hypertrophic obesity, such an investigation remains unexplored." (PMID 37794318, 2023). "Perhaps, the link between CCN5 and GDM is related to the positive correlation of CCN5 with inflammatory cytokines and insulin resistance as probable mechanisms." (PMID 37794318, 2023). "Based on our findings, there appears to be a noteworthy and affirmative correlation between serum levels of CCN5 and the risk of developing GDM, as well as its associated risk factors such as BMI, insulin resistance index, FBG, and inflammatory cytokines TNF-α and IL-6." (PMID 37794318, 2023). "Our research indicates a noteworthy and affirmative correlation between the levels of CCN5 in the serum and the risk of developing GDM, along with its associated risk factors such as BMI, insulin resistance index, FBG, and inflammatory cytokines (TNF-α and IL-6)." (PMID 37794318, 2023). "This suggests that CCN5 may play a role in the development of GDM, as there was a direct and significant correlation between CCN5 and several risk factors for GDM, including BMI, insulin resistance index, FBG, and inflammatory cytokines (IL-6 and TNF-α)." (PMID 37794318, 2023). "Therefore, it is plausible that increased expression of CCN5 could inhibit PPARγ and subsequently contribute to insulin resistance and diabetes through the formation of an additional complex with Zfp423." (PMID 37794318, 2023). "Overexpression of CCN5 in the adipose tissue of mice induced hyperplasia of cardiomyocytes, as well as of WAT and BAT, and prevented HFD-induced insulin resistance." (PMID 30485307, 2018).
myocardial infarction (6 papers, 2020 to 2025). Gross necrosis of the myocardium, as a result of interruption of the blood supply to the area, as in coronary thrombosis. "Thus, neurohormonal activation subsequent to myocardial infarction and impairment of cardiac function may conceivably cause activation of transcription from the CCN5 promoter." (PMID 34854055, 2022). "The present study reports data from investigations on transcriptional regulation and analysis of cellular distribution of CCN5 in the heart after myocardial infarction." (PMID 34854055, 2022). "Further, high mRNA and protein levels of CCN5 were found in the granulation tissue and differentiating scar tissue after myocardial infarction." (PMID 34854055, 2022). "Tissue distribution of CCN5 in hearts from healthy mice and from mice subjected to myocardial infarction was investigated." (PMID 34854055, 2022). "The finding of increased CCN5 mRNA levels in the healing wound following myocardial infarction indicates that the cells of the developing scar, such as endothelial cells, fibroblasts, or leukocytes may be the sources of CCN5." (PMID 34854055, 2022). "In the developing scar tissue replacing the myocardial necrosis 4 weeks after induction of myocardial infarction, CCN5 immunoreactivity was observed in endothelial cells of capillaries and other microvessels, mononuclear leukocytes, and spindle-shaped fibroblast-like cells." (PMID 34854055, 2022). "The early inflammatory phase following myocardial infarction with soaring levels of TNF-α may provide basis for the delayed increase of CCN5 relative to CCN2." (PMID 34854055, 2022). "While the distribution and regulation of CCN2 in the heart following myocardial infarction is well described, that of CCN5 is largely unknown." (PMID 34854055, 2022). "We hypothesized that CCN5 would alleviate the adverse effects of myocardial infarction (MI) through its anti-fibrotic properties under stress conditions." (PMID 38892449, 2024). "We also find that CCN5 transcription is repressed by TNF-α, an inflammatory mediator highly elevated in early phases of wound healing following myocardial infarction." (PMID 34854055, 2022). "The mechanisms of the delayed induction of CCN5 relative to CCN2 following myocardial infarction has not yet been resolved." (PMID 34854055, 2022). "Similar distribution of CCN5 was observed in non-ischemic myocardial tissue of the mice subjected to myocardial infarction." (PMID 34854055, 2022).
diabetes (5 papers, 2018 to 2025). "We next examined whether the obese phenotypes observed in the CCN5 KO mice are associated with diabetes." (PMID 30485307, 2018). "The CCN5 KO mice also exhibited mild diabetes characterized by high fasting glucose levels and impaired insulin and glucose tolerances." (PMID 30485307, 2018). "In a mouse pancreatic islet study, gene expression and protein levels of CCN5 were upregulated under the influence of IGF-1, leading to the activation of AKT and ERK2 and contributing to the growth and survival of pancreatic beta cells, thus improving the condition of diabetes." (PMID 37794318, 2023).
fibrosis (5 papers, 2018 to 2025). the formation of excess fibrous connective tissue in an organ or tissue in a reparative or reactive process. "We previously reported that the matricellular protein CCN5 elicits cardioprotective signalling that prevents the formation of massive ventricular fibrosis in response to chronic pressure overload." (PMID 32885578, 2020). "We further showed that CCN5 overexpression following TAC reverses pre‐established ventricular fibrosis by promoting myofibroblast‐specific apoptosis." (PMID 32885578, 2020). "In this study, we attempted to reduce cardiac fibrosis, which in turn improved cardiac function in a DMD mouse model, through CCN5 gene transfer." (PMID 35557546, 2022). "TGFβ mediates cardiac fibrosis and CCN5/WISP2 expression is strongly downregulated in patients with heart failure whereas CTGF is increased." (PMID 29247377, 2018).
gastric cancer (5 papers, 2019 to 2025). A primary or metastatic malignant neoplasm involving the stomach. "We found that IGFBP7 and CCN5 had significant abnormal expression between gastric cancers and adjacent normal tissues, and these two IGFBP-rPs were associated with both overall survival and disease-free survival of gastric cancer patients." (PMID 37304887, 2023). "Differential expression analysis showed that IGFBP7, CCN2, ESM1, CCN4 and CCN6 mRNA were over-expressed in gastric cancer tissues while CCN5 mRNA was down-expressed (all p < 0.05)." (PMID 37304887, 2023). "From overall survival analysis, gastric cancer patients with high expression of IGFBP7, CCN2, CCN3, CCN1, CCN5 or CCN4 would have a poor survival time (all p < 0.05)." (PMID 37304887, 2023).
breast adenocarcinoma (4 papers, 2020 to 2023). "Full-length CCN5 has previously been reported to induce estrogen receptor ER-α mRNA in triple negative MDA-MB-231 mammary adenocarcinoma cells and to inhibit EMT." (PMID 36529291, 2023). "CCN5 TSP1 induced expression of estrogen receptor-α in triple negative MDA-MB-231 mammary adenocarcinoma cells and inhibited epithelial-to-mesenchymal transition (EMT) in the same cells." (PMID 37245184, 2023). "Full-length CCN5 has previously been reported to restore responsiveness of triple negative MDA-MB-231 mammary adenocarcinoma cells to estrogens by induction of ER-α mRNA." (PMID 36529291, 2023). "TSP1 from CCN5 induced expression of estrogen receptor-α and inhibited EMT in triple negative MDA-MB-231 mammary adenocarcinoma cells." (PMID 37245184, 2023). "The TSP1 domain of CCN5 also recapitulated a positive regulatory function previously assigned to full-length CCN5, that is, induction of ER-α expression in triple negative MDA-MB-231 mammary adenocarcinoma cells." (PMID 36529291, 2023).
heart failure (4 papers, 2018 to 2024). Inability of the heart to pump blood at an adequate rate to meet tissue metabolic requirements. "The anti-fibrotic effects of CCN5/WISP2 were further validated in patients with heart failure." (PMID 29247377, 2018). "Interestingly, the anti-fibrotic effect of CCN5/WISP2 is protective against heart failure by inhibition of the TGFβ pathway." (PMID 29247377, 2018).
Nephroblastoma (4 papers, 2015 to 2022). An embryonal neoplasm characterized by the presence of epithelial, mesenchymal, and blastema components. "The CCN family includes CCN1/CYR61 (cystein-rich 61], CCN2/CTGF (connective tissue growth factor), CCN3/NOV (nephroblastoma overexpressed), and also CCN4/WISP-1, CCN5/WISP-2, CCN6/WISP-3 (Wnt-inducible secreted proteins)." (PMID 34940056, 2021). "Wnt-1 inducible signaling pathway protein-2 (WISP-2), also known as CCN5, is a 29-kDa secreted protein that is a member of the connective tissue growth factor (CTGF) and nephroblastoma over-expressed gene family of matricellular proteins, and is critical in growth factor mediated cell proliferation." (PMID 25435966, 2015).
cardiomyopathy (3 papers, 2018 to 2025). A disease of the heart muscle or myocardium proper. "For example, it would be interesting to see if CCN5 KO specifically in hearts also leads to lipotoxic cardiomyopathy to a comparable level seen in the whole body CCN5 KO." (PMID 30485307, 2018). "Therefore, our data suggest that lipotoxic cardiomyopathy is generated as a result of CCN5 KO in mice." (PMID 30485307, 2018). "Therefore, we hypothesized that CCN5 might have a beneficial effect on cardiac fibrosis and function in DMD-associated cardiomyopathy." (PMID 35557546, 2022). "Therefore, we hypothesized that CCN5 gene transfer would ameliorate cardiac fibrosis and thus improve cardiac function in DMD-induced cardiomyopathy." (PMID 35557546, 2022).
ductal carcinoma in situ (3 papers, 2018 to 2025). "Notably, CCN5 expression level has been reported to be associated with delayed progression of ductal carcinoma in situ to invasive carcinoma." (PMID 39144722, 2024). "Given the complex interactions between CCN5, ER, and progression of BC, the aim of the current study was to analyse the expression of CCN5 and ER in normal breast tissue, ductal carcinoma in situ (DCIS), and invasive carcinoma tissues of patients with advanced BC." (PMID 40016720, 2025).
type 2 diabetes (3 papers, 2017 to 2018). "CCN5/WISP2 was also positively correlated with markers of ectopic fat accumulation (i.e.,fat in liver or non-subcutaneous / intra-abdominal adipose tissue) and negatively correlated with whole-body insulin sensitivity, a marker of risk of developing type 2 diabetes." (PMID 29247377, 2018).
Hypertension (2 papers, 2020 to 2021). The presence of chronic increased pressure in the systemic arterial system. "In cardiac muscle fibrosis associated with hypertension, CCN5/WISP-2 levels are reduced." (PMID 34063397, 2021). "Our experimental model of high Ang II-induced hypertensive HF revealed that CCN5 was downregulated in the high Ang II SHR and increased via Ang II production inhibition by ACEI treatment." (PMID 33013358, 2020). "Our rat model of essential hypertensive HF revealed a significant decrease of CCN5 in high Ang II-induced hypertensive HF." (PMID 33013358, 2020). "In our study, we confirmed the anti-fibrotic ability of endogenous CCN5 in high Ang II-induced hypertensive HF." (PMID 33013358, 2020). "In summary, we verifiy the essential role of endogenous CCN5 in high Ang II-induced hypertensive HF." (PMID 33013358, 2020). "To verify the essential role of CCN5 in hypertension, firstly we detected decreased CCN5 levels, but elevated CCN2 levels in all hypertensive patients." (PMID 33013358, 2020). "Moreover, we elucidated the indispensable role of endogenous CCN5 in high Ang II-induced hypertensive HF." (PMID 33013358, 2020). "Using our experimental model of high Ang II-induced hypertensive HF along with elevated expression of Ang II in both serum and myocardial tissue, we evaluated whether downregulation of CCN5 could affect the cardiac structure, function, and myocardial fibrosis." (PMID 33013358, 2020). "Although several studies have reported the anti-fibrotic effects of exogenous CCN5 in HF, the roles of endogenous CCN5 in high Ang II-induced hypertensive HF still remain unclear." (PMID 33013358, 2020). "CCN5 expression could be elevated by inhibiting Ang II, which provided a cardioprotective effect in hypertension-induced HF." (PMID 33013358, 2020). "We hypothesized that endogenous CCN5 plays an essential role in TGF-β1/Ang II networking-induced CF which accelerates the development of hypertensive HF." (PMID 33013358, 2020).